MIR6499 (microRNA 6499)
Synonyms: hsa-mir-6499; mir-6499
Gene: MicroRNA gene on chromosome 5 (151,522,087 to 151,522,148, reverse strand). Ensembl gene ENSG00000276622.
Homologues: Orthologues: chimpanzee MIR6499 (100% identical).